KPNA2 (karyopherin subunit alpha 2)
Diseases named in the same sentence as KPNA2 in open-access papers (continued):
Sharing a sentence is not in itself a finding about the gene and the disease.
ischemia (1 paper, 2022). A hypoperfusion of the BLOOD through an organ or tissue caused by a PATHOLOGIC CONSTRICTION or obstruction of its BLOOD VESSELS, or an absence of BLOOD CIRCULATION. "Briefly, our study shows that under hypoxic conditions, the expression of KPNA2 was upregulated in a hindlimb ischemia model and endothelial hypoxia and that the binding of KPNA2 and STAT3 was increased under hypoxic conditions, which promoted angiogenesis under hypoxic conditions." (PMID 36578083, 2022).
kidney cancer (1 paper, 2021). Primary or metastatic malignant neoplasm involving the kidney. "Further, the expression of KPNA2 is positively correlated with NPM1 in kidney cancer." (PMID 34469024, 2021). "To assess whether NPM1 contributes to the proliferation and migration progression of kidney cancer through the regulation of KPNA2, we transfected KPNA2‐targeting siRNA into ACHN cells with forced expression of NPM1." (PMID 34469024, 2021). "Next, in in vitro and vivo analysis, our results indicated that KPNA2 may regulate NPM1 to promote the progression of kidney cancer." (PMID 34469024, 2021). "We then investigated the effect of KPNA2 knocked down on kidney cancer cell lines." (PMID 34469024, 2021). "Knockdown of KPNA2 successfully repressed the cell viability of kidney cancer cells." (PMID 34469024, 2021). "These in vitro data demonstrated that KPNA2 has an impact on metastasis of kidney cancer cells." (PMID 34469024, 2021). "So, KPNA2 may regulate NPM1 via c‐Myc to promote the proliferation of kidney cancer cells." (PMID 34469024, 2021).
kidney tumour (1 paper, 2021). "In order to investigate the role of KPNA2 in kidney tumour, functional studies were performed in 786‐O and ACHN cell lines." (PMID 34469024, 2021). "The expression of KPNA2 was examined in three types of kidney tumour cell lines, including 786‐O, ACHN and Caki‐1." (PMID 34469024, 2021). "Repression of KPNA2 was proved to be efficient to repress tumorigenesis and development of kidney tumour in in nude mice." (PMID 34469024, 2021). "Our results showed that down‐regulation of KPNA2 inhibited the proliferation and invasion of kidney tumour cell cells in vitro, while the cell cycle arrest and cellular apoptosis were induced once KPNA2 was silenced." (PMID 34469024, 2021). "Therefore, the possible function of KPNA2 in kidney tumour cell proliferation was investigated at the following five days after 3 days postinjection." (PMID 34469024, 2021). "In this study, we aim to investigate the roles of KPNA2 in kidney tumour development." (PMID 34469024, 2021). "We further examined the cell cycle distribution of kidney tumour cells after deregulated KPNA2." (PMID 34469024, 2021). "The results indicated that knockdown of KPNA2 promotes kidney tumour cell apoptosis." (PMID 34469024, 2021). "Further analysis based on siRNA (small interfering RNA) of KPNA2 demonstrated the key role of KPNA2 in kidney tumour cell proliferation, migration and apoptosis, which grants it one of the most promising biomarkers and therapeutic targets for early diagnosis of kidney tumour." (PMID 34469024, 2021).
lipodystrophy (1 paper, 2009). A congenital or acquired disorder characterized by abnormal loss or redistribution of the adipose tissue in the body. "Others include suppression of Lpin3, a candidate gene for human lipodystrophy; Kpna2, an importin; and AKAP12, a tumor suppressor." (PMID 18925475, 2009).
lymphoma (1 paper, 2015). A malignant (clonal) proliferation of B- lymphocytes or T- lymphocytes which involves the lymph nodes, bone marrow and/or extranodal sites. "In addition, a smaller fraction of the significantly mutated genes, such as PSMA1 and KPNA2, have not been reported in human lymphoma but have been reported in other human cancers." (PMID 26377837, 2015).
male infertility (1 paper, 2024). The inability of the male to effect fertilization of an ovum after a specified period of unprotected intercourse. "(j) LoF variants in the orthoBackbone genes HSPA2 and KPNA2 are potentially associated with human male infertility." (PMID 39388236, 2024). "The translational application of our cross-species platform in human reproductive healthcare has so far uncovered three new genes associated with human male infertility (RNF113B, HSPA2, and KPNA2)." (PMID 39388236, 2024). "Filtering these exomes for LoF variants in the 27 selected orthoBackbone genes revealed two new human male infertility candidate genes: HSPA2 and KPNA2." (PMID 39388236, 2024).
meningioma (1 paper, 2024). A generally slow growing tumor attached to the dura mater. "Although only in single studies, KPNA2, CDK6, Cox-2, MCM7 and PCNA are proposed as additional markers with high expression that are related with poor prognosis of meningioma patients." (PMID 38758750, 2024).
Merkel cell carcinoma (1 paper, 2013). "Non-squamous cell malignant tumors of the skin including Paget’s disease, Merkel cell carcinoma, and mycosis fungoides also showed diffuse, intense staining of KPNA2, indicating significantly higher expression in skin malignancy." (PMID 24098495, 2013).
metastatic prostate carcinoma (1 paper, 2018). A carcinoma that arises from the prostate gland and has spread to other anatomic sites. "We also observed downregulation of KPNA2, an importin and a key marker of poor disease prognosis and metastatic prostate cancer aggressiveness." (PMID 29464047, 2018).
mixed ovarian germ cell tumors (1 paper, 2012). "RT-PCR showed that KPNA2 expression in 3 different histological types of OMGCT(including 4 yolk sac tumors, 5 immature teratomas, and 6 mixed ovarian germ cell tumors), was higher than normal ovarian tissues and mature teratomas." (PMID 22962582, 2012).
Nijmegen breakage syndrome (1 paper, 2014). Nijmegen breakage syndrome is a rare genetic disease presenting at birth with microcephaly, dysmorphic facial features, becoming more noticeable with age, growth delay, and later-onset complications such as malignancies and infections. "The deletion of KPNA2 and its association with NBN links Patient 3 to Patients 1 and 2 and the well-established phenotypic overlap of LIG4 and Nijmegen breakage syndrome." (PMID 24892279, 2014). "KPNA2 has a role in nucleocytoplasmic transport and is responsible for the import, via its nucleus localization sequence, of NBN, the DNA repair gene mutated in Nijmegen breakage syndrome." (PMID 24892279, 2014).
osteoarthritis (1 paper, 2020). A noninflammatory degenerative joint disease occurring chiefly in older persons, characterized by degeneration of the articular cartilage, hypertrophy of bone at the margins and changes in the synovial membrane. "The expression of karyopherin alpha 2 (KPNA2), which regulates delivery of p65 to the nucleus, also increased in osteoarthritis." (PMID 32189997, 2020).
ovarian clear cell adenocarcinoma (1 paper, 2021). A malignant glandular epithelial neoplasm characterized by the presence of clear and hobnail cells. "KPNA2 expression was significantly higher in ovarian mucinous adenocarcinoma, ovarian endometrioid adenocarcinoma, ovarian clear cell adenocarcinoma, ovarian serous adenocarcinoma, ovarian serous surface papillary carcinoma, ovarian serous cystadenocarcinoma." (PMID 34034774, 2021). "Using Oncomine, we found that KPNA2 is significantly upregulated in ovarian mucinous adenocarcinoma, ovarian endometrioid adenocarcinoma, ovarian clear cell adenocarcinoma, ovarian serous adenocarcinoma, ovarian serous surface papillary carcinoma, and ovarian serous cystadenocarcinoma." (PMID 34034774, 2021).
pancreatic ductal adenocarcinoma (1 paper, 2022). An infiltrating adenocarcinoma that arises from the epithelial cells of the pancreas. "In pancreatic ductal adenocarcinoma, KPNA2 expression in adenocarcinoma was significantly suppressed in well‐differentiated cases." (PMID 35860570, 2022).
Parkinson disease (1 paper, 2021). A progressive degenerative disorder of the central nervous system characterized by loss of dopamine producing neurons in the substantia nigra and the presence of Lewy bodies in the substantia nigra and locus coeruleus. "KPNA2 and KPNA6 have been identified as substrates of LRRK2/PARK864 whose mutations cause one of the most common forms of Parkinson’s disease." (PMID 34019093, 2021).
renal cell carcinoma (1 paper, 2021). "However, comprehensive studies of KPNA2 functions in renal cell carcinoma (RCC) are still lacking." (PMID 34469024, 2021).
Russell-Silver syndrome (1 paper, 2012). "KPNA2 has also been associated with the Russell-Silver syndrome and possess tumorigenic activity." (PMID 22962582, 2012).
sarcoma (1 paper, 2020). A usually aggressive malignant neoplasm of the soft tissue or bone. "This is the first report of a correlation between KPNA2 expression and sarcoma." (PMID 33176814, 2020).
SARS-CoV infection (1 paper, 2023). "During SARS-CoV infection, karyopherin 2 (KPNA2) in complex with KPNB1 were retained at the ER/Golgi, while KPNA2 was detected in the nucleus in SARS-CoV-Δ6 infection." (PMID 37197199, 2023).
teratoma (1 paper, 2012). A non-seminomatous germ cell tumor characterized by the presence of various tissues which correspond to the different germinal layers (endoderm, mesoderm, and ectoderm). "KPNA2 was found to be over-expressed by approximately eight-fold in yolk sac tumors and immature teratomas compared to normal ovarian tissue by microarray assays." (PMID 22962582, 2012). "Similar to various OMGCTs, KPNA2-extensive expression immature teratomas patients have a significantly lower OS and DFS when compared to KPNA2-negative patients (P = 0.0012, P = 0.0006, respectively)." (PMID 22962582, 2012). "KPNA2 was down-expressed in the normal ovarian specimens but extensively overexpressed in 2 yolk sac tumors and 2 immature teratomas." (PMID 22962582, 2012). "KPNA2 was down-expressed in normal ovarian tissue but extensively over-expressed in 2 yolk sac tumors and 2 immature teratoma." (PMID 22962582, 2012). "Moreover, kaplan-Meier survival curves show that immature teratoma patients exhibiting higher KPNA2 expression had substantially lower survival rates than the patients who had lower KPNA2 expression." (PMID 22962582, 2012).
triple-negative breast carcinoma (1 paper, 2022). An invasive breast carcinoma which is negative for expression of estrogen receptor (ER), progesterone receptor (PR), and human epidermal growth factor receptor 2 (HER2). "Our analyses of existing clinical datasets for expression and survival outcomes show that KPNA2 over-expression contributes to poor patient survival outcomes, further necessitating its investigation in future studies to consider its clinical utility for triple negative breast cancer subtypes." (PMID 35948941, 2022).
vascular tumour (1 paper, 2022). "The KPNA2, LPCAT1, KIF2C, and SPP2 genes were statistically correlated with pathological stage, histologic grade, ECOG, vascular tumour cell type, and tumour status." (PMID 35915607, 2022).
tumor (96 papers, 2009 to 2026). "Analysis revealed a significant association between KPNA2 protein expression and tumor grade in BC patients (p = 0.049)." (PMID 40002266, 2025). "Validation of this finding showed that high KPNA2 expression is significantly associated with more advanced tumor stages in the TCGA-BRAC cohort (p = 0.004)." (PMID 40002266, 2025). "The expression levels of KPNA1 and KPNA2 were significantly associated with the tumor histologic grade." (PMID 35991835, 2022). "The top up-regulated factor in both signatures was the karyopherin subunit alpha 2 (Kpna2), a nuclear transporter involved in the nucleocytoplasmic transport pathway of several tumor-associated proteins, including MYC and E2Fs." (PMID 36269833, 2022). "The results proved KPNA2 was up‐regulated in the late stage of ccRCC, and higher KPNA2 is associated with poor survival rate of patients, demonstrating that the expression level of KPNA2 in tumour tissue has a good prognostic value for ccRCC." (PMID 34469024, 2021). "Although KPNA2 was implicated in many inflammatory processes, and its tumor-promoting activities in HCC were shown in many studies, its associations with immune response in HCC and their clinical significance were not clearly illustrated." (PMID 33193737, 2020). "KPNA2 is upregulated in a large variety of tumor types and its elevated expression is associated with an increased degree of malignancy, tumor spread and poor patient outcome." (PMID 29580221, 2018). "KPNA2 is implicated in the malignant transformation of cells by regulating the DNA-repair proteins, the activation of apoptosis and the transport of tumour suppressors, transcription factors and oncogenes into the nucleus." (PMID 30323892, 2018). "Many studies have indicated that the aberrant expression of KPNA2 is closely associated with tumor genesis and cancer progression." (PMID 27974678, 2017). "KPNA2 overexpression positively correlates with the poor prognosis of cancer patients and is associated with tumor invasiveness." (PMID 27009856, 2016). "A univariate Cox regression analysis revealed that male sex (P = 0.004), tumors located in the ureter (P = 0.015), multiple tumor foci (P = 0.009),high stage(P = 0.012) and high KPNA2 expression (P < 0.001) were highly associated with a shorter DFS." (PMID 25956057, 2015). "The luminal A sub-networks of up-regulated genes pointed to functions associated to genome instability and mutation (EIF4A3), and tumor-promoting inflammation (KPNA2)." (PMID 25625699, 2015). "Recent studies suggest KPNA2 expression is induced in tumor cells and is strongly associated with prognosis, although the precise roles and mechanisms of KPNA2 overexpression in proliferative disorders have not been defined." (PMID 24098495, 2013). "Moreover, exosomal KPNA2 in BCa tissues emerges as a promising diagnostic marker, aiding fibroblast transformation into CAFs and disrupting tumor interactions." (PMID 39956902, 2025). "The activation of MYC in Fh1-deficient cells, which was previously hypothesized, led to increased expression of the karyopherin subunit alpha 2 (Kpna2), a nuclear transporter involved in the nucleocytoplasmic transport of several tumour-associated factors." (PMID 37689804, 2023). "In TSCC, KPNA2 levels were associated with clinical prognosis and tumor grade." (PMID 35860570, 2022). "We found that DEGs exhibited close associations, among which the centrally located CCNB1 and KPNA2 may have potential roles in tumor progression." (PMID 36333388, 2022).
tumor (continued). "Karyopherin alpha 2 (KPNA2) belongs to the family of karyopherin, the nuclear transport proteins; any aberrant expression or dysfunction of these transporter proteins were shown to be associated with tumorigenesis and tumor progression." (PMID 31581454, 2019). "KPNA2 could promote carcinogenesis mainly through the translocation of cancer-associated cargo proteins, including proteins with tumor-suppressive or oncogenic properties." (PMID 26204489, 2015). "We also found a positive association between KPNA2 expression and advanced tumor stage, indicating that KPNA2 might play a critical role in the progression of colon cancer." (PMID 26626145, 2015). "Immunohistochemistry results indicated that high expression of KPNA2 expressed significant association with a poor tumor grade, an advanced FIGO stage, recurrence and uncontrolled, resistance/refraction to initial chemotherapy, and SALL4 level in these patients." (PMID 22962582, 2012). "Additionally, KPNA2 from BCa cells triggered the conversion of fibroblasts into cancer-associated fibroblasts (CAFs), which secreted elevated levels of interleukin-6 (IL-6), contributing to a tumor-supporting environment." (PMID 39956902, 2025). "Similarly, GO analysis revealed that several hallmarks of the tumor were enriched in the high-KPNA2 subgroup, such as DNA replication and cell cycle G2/M phase transition, while genes in the low KPNA2 subgroup was associated with immune response, bone resorption and bone remodeling." (PMID 36199790, 2022). "Plasma exosomes from patients with BCa exhibited notably increased levels of KPNA2 compared with healthy controls, suggesting KPNA2 as a potential new tumor indicator." (PMID 39956902, 2025). "The low KIFC1 expression group had smaller tumor sizes (p = 0.02), while the low KPNA2 group was predominantly at the Tis-T1 stage (p = 0.005)." (PMID 39956902, 2025). "Results showed that KPNA2 overexpression diminished miR-26b-5p’s inhibitory effect on tumor growth, implying miR-26b-5p targets KPNA2 to suppress tumors." (PMID 39956902, 2025). "By modulating processes such as cell differentiation, proliferation, and apoptosis, KPNA2 facilitates tumor growth and progression." (PMID 40918463, 2025). "Functional assays revealed that KPNA2 knockdown suppressed telomerase activity, inhibited tumor cell proliferation and metastasis, whereas its overexpression produced the opposite effects." (PMID 40665355, 2025). "Functional analyses demonstrated that KPNA2 knockdown inhibited telomerase activity, tumor cell proliferation, and metastasis, whereas its overexpress." (PMID 40665355, 2025). "Further analysis of the MMH cohort revealed that a high or low expression (transcript levels lower or higher than the cohort median) of KPNA2/FOXM1/CCNB1/CCNB2 is associated with ER, PR, HER2, and Ki67 status, molecular subtype, tumor grade, and AJCC stage." (PMID 40002266, 2025). "The results showed that KPNA2 mRNA expression was significantly elevated in tumor tissues compared to adjacent normal tissues." (PMID 40665355, 2025). "Overexpression of KPNA2 positively affects tumor differentiation, stage and vascular invasion, and can predict early recurrence and poor prognosis of HCC." (PMID 40918463, 2025). "Compared to normal samples, G6PD and KPNA2 exhibited significant expression peaks in the early cellular phases in tumor samples, and more homogeneous expression distribution was displayed in normal samples." (PMID 40307857, 2025). "Our analysis revealed significantly elevated serum exo-KPNA2 levels in tumor patients compared with healthy individuals." (PMID 39956902, 2025). "KPNA2, also known as Rch1 or hSRP1, plays a significant role in cell signaling and nuclear-cytoplasmic transport, affecting tumor progression." (PMID 39956902, 2025). "Drawing from the TCGA-BLCA cohort, we discovered that RAD54B and KPNA2 expressions rose in tumor tissues, whereas TPM1 expressions declined in comparison to corresponding normal tissues." (PMID 38735911, 2024).